RHOA (ras homolog family member A)
Diseases named in the same sentence as RHOA in open-access papers (continued):
Sharing a sentence is not in itself a finding about the gene and the disease.
keloid (6 papers, 2016 to 2025). An irregularly shaped, elevated mark on the skin caused by deposits of excessive amounts of collagen during wound healing. "Another prominent protein found in keloid ECM is periostin, a stromal cell protein that promotes keloid formation by activating the RhoA pathway to promote TGF-β1 secretion." (PMID 35614943, 2022). "Therefore, targeting the expression of ET-1 or blocking the RhoA/ROCK pathway may provide powerful approaches for inhibiting ET-1-induced keloid." (PMID 37809065, 2023). "Furthermore, type I collagen, CTGF and α-SMA are each upregulated via the activation of RhoA signaling in keloid fibroblasts, which may be reversed by Simvastatin." (PMID 27611832, 2016). "We then compared the expression of RhoA and ROCK2 in fibroblasts from 10 normal skin samples, 10 hypertrophic scars, and 10 keloids by qPCR and western blot." (PMID 39781462, 2025). "In human keloid fibroblasts, simvastatin inhibited TGF-β-induced RhoA activation and RhoA/ROCK signaling by interfering with posttranslational geranylgeranylation of RhoA." (PMID 33597925, 2020). "Notably, the RhoA/Rho-kinase (ROCK) pathway can be activated by ET-1 to promote myofibroblast differentiation and ECM accumulation in the dermis, thereby markedly participating in the pathophysiology of abnormal scar/keloid formation." (PMID 37809065, 2023).
kidney damage (6 papers, 2016 to 2024). "Dex is possible to inhibit the expression of α-SMA and renal fibrous substance deposition in rat kidney via RhoA/ROCK/Nox4 signaling pathway, thereby reducing early kidney damage in model rats." (PMID 31844679, 2019). "Since the discovery of Fasudil and Y-27632, two selective inhibitors of RhoA and ROCK have generated great interest as important regulators in diverse models of kidney damage." (PMID 29570626, 2018). "Thus, both RhoA and ROCK inhibitions have been proposed as treatments to prevent hypertension and kidney damage." (PMID 29570626, 2018).
liver cirrhosis (6 papers, 2015 to 2025). "RhoA is reportedly known to be involved in stress fiber formation in liver cirrhosis and adhesion complexes formation." (PMID 34469466, 2021). "Furthermore, Rgkl ameliorated liver cirrhosis by modulating LSEC metabolic functions via the CD36/PPAR/CPT-1 pathway and suppressing HSC activation through the RhoA/ROCK/YAP and PI3K/AKT/NF-κB pathways." (PMID 41039598, 2025). "Also in experimental models of toxic liver cirrhosis levels of total c-SRC remained unchanged, while RhoA was significantly increased." (PMID 26696895, 2015). "As shown for experimental liver cirrhosis, also in human liver cirrhosis RhoA expression is highly upregulated compared to the non-cirrhotic control liver samples." (PMID 26696895, 2015). "The findings presented here are also of relevance to liver cirrhosis, characterized by activation of stellate cells, in part by a non-canonical SHH/RHOA axis." (PMID 30148884, 2018). "Since this crosstalk of RhoA and c-SRC could be observed in cholestatic and toxic models of liver cirrhosis, as well as in alcohol-induced human liver cirrhosis, our data suggest that the mechanisms are independent of the etiology." (PMID 26696895, 2015).
mental retardation (6 papers, 2016 to 2022). "Misregulated RhoA, Rac1/Rac3 and cdc42 activity has been linked with intellectual disability (ID) and other neurodevelopmental conditions that comprise ID." (PMID 29925821, 2018). "Specific defects in molecular regulation of the RhoA/Rho kinase signaling pathway, e.g. inactivating mutation in a Rho GTPase- activating protein, cause specific X-linked form(s) of human mental retardation characterized by abnormal dendritic spine morphology and/or density." (PMID 27441369, 2016). "RHOA is a member of the RHO GTPase involved in several intellectual disabilities that affect dendritic structure in adult neurons, a phenotype also described in certain DS models or linked to DYRK1A." (PMID 33693642, 2021). "Therefore, it is not surprising that RhoA activity has been related to developmental disabilities, such as mental retardation." (PMID 35328827, 2022).
metastatic cancer (6 papers, 2014 to 2022). A carcinoma which has spread from the original site of growth to another anatomic site. "PDPN is frequently upregulated in metastatic cancers to induce RhoA activity and promote cell migration and invasion." (PMID 24618420, 2014). "Interestingly, RhoA gene expression is induced by the Skp2/Myc/Miz1 complex, whose overexpression is correlated with RhoA expression in metastatic cancer." (PMID 36180910, 2022). "Ultimately, both tumor cell-intrinsic and extrinsic signals may shape the acquisition of MetRes features in brain metastatic cancer cells via RhoA and SRF." (PMID 36509758, 2022). "We therefore investigated whether the MEK1/2-ERK mediated feedback loop, which is required to maintain RhoA activity at the leading edge influenced cell motility within 3D ECM that resembles interstitial matrix encountered by metastatic cancer cells." (PMID 27138333, 2016). "Here we show that an actin depolymerising agent, Cyt D, reduces cell size and shape, inactivates RhoA and induces expression of E-cadherin, defining the actin cytoskeleton as an upstream regulator of EMT in metastatic cancer cells." (PMID 25756282, 2015).
oral cancer (6 papers, 2014 to 2025). "OSF significantly induced the EMT in oral cancer cells and downregulated epithelial markers, such as E‐cadherin, but significantly elevated vimentin, fibronectin, N‐cadherin, RhoA, Rac‐1 and FAK." (PMID 34528373, 2021). "It increased the expressions of RhoA and Rho-associated, coiled-coil containing protein kinase-1 (ROCK1), but inhibited the expression of NF-κB p65 in SAS Human oral cancer cells." (PMID 31791311, 2019). "Further, the inhibition of G12 signaling by regulator of G-protein signaling (RGS) inhibited Gα12-mediated RhoA activation, which in turn resulted in reduced LN metastases in a tongue-orthotopic xenograft mouse model of oral cancer." (PMID 25275299, 2014). "The phytochemical study on Quercus infectoria identified several gallotannins, including 6‐O‐digalloyl‐1,2,3,4‐tetra‐O‐galloyl‐β‐D‐glucose, with a strong binding affinity against oral cancer targets such as MMP‐2, NF‐κB p65, and RhoA, showing binding energies up to −10.6 kcal/mol (AutoDock v4.2.6)." (PMID 40933552, 2025). "Thus, when 4-carbomethoxyl-10-epigyrosanoldie E inhibits RhoA expression, this leads to a decrease in MMP-2 and MMP-9 levels, impacting the migration and invasion of Cal-27 and Ca9-22 oral cancer cells." (PMID 38374934, 2024).
osteoporosis (6 papers, 2016 to 2024). A condition of reduced bone mass, with decreased cortical thickness and a decrease in the number and size of the trabeculae of cancellous bone (but normal chemical composition), resulting in increased fracture incidence. "We hypothesized that RhoA not only plays an important role in the pathogenesis of RA synovitis but also participates in the activation of OC, causing bone erosion and osteoporosis in RA." (PMID 38022686, 2023). "Here, we have observed RhoA activation in some of CD68+ cells accumulating at the pathological sites, suggesting a potential role for RhoA in activating osteoclasts, mediating osteoporosis of the bone tissue and promoting inflammation in dKO mice." (PMID 33361519, 2020). "In mevalonate pathway, fluvastatin inhibited HMG-CoA reductase and prenylation of RhoA in low-turnover osteoporosis." (PMID 30142209, 2018). "OVX-induced osteoporosis in mice was prevented when RhoA was knocked out, indicating that this might be a potential therapy option for osteoporosis and other bone-resorption disorders in people." (PMID 37020186, 2023). "Following these results, it appears that targeting RhoA may be a promising technique for osteoporosis and other bone-resorption disorders." (PMID 37020186, 2023). "RhoA promoted osteoclast development via the Akt-mTOR-NFATc1 signaling pathway, resulting a osteoporosis phenotype, and that manipulating RhoA activity might be a therapeutic strategy for osteoporotic bone loss." (PMID 37020186, 2023). "Furthermore, we investigated the involvement of RhoA in an ovariectomized (OVX) animal model of osteoporosis to determine the possible therapeutic implications of RhoA-Rock." (PMID 37020186, 2023). "Importantly, RhoA signaling has been shown to regulate podosome assembly, polarization, function and survival of osteoclast cells, suggesting a potential mechanism for RhoA in regulating osteoporosis in DMD mice." (PMID 33361519, 2020). "Sema4D-/- mice demonstrate a mild osteosclerotic phenotype, identical to Plexin-B1−/− mice and mice expressing dominant-negative RhoA, so this signaling pathway could have therapeutic implications in diseases such as osteoporosis." (PMID 26910109, 2016). "Notably, OxLDL activates the RhoA/ROCK signaling pathway, increasing osteoclast resorptive activity and inhibiting the expression of bone formation-related genes, further exacerbating osteoporosis." (PMID 39839298, 2024).
renal cell carcinoma (6 papers, 2012 to 2021). "Honokiol inhibits the migration of renal cell carcinoma through activation of the RhoA/ROCK/MLC signaling pathway and by targeting KISS1/KISS1R signaling." (PMID 34671554, 2021). "We now show that Activin B and RhoA signaling have opposing roles in these processes in renal cell carcinoma cells." (PMID 25343250, 2014). "Taken together, these findings reveal a novel paradigm in which loss of the FLCN-p0071 interaction and consequent defects in cell-cell adhesion, cell polarity and RhoA activity participates in the pathogenesis of renal cell carcinoma, skin tumors, and cystic airspace enlargement." (PMID 23139756, 2012).
skin tumor (6 papers, 2012 to 2024). "In line with our findings, RhoA has been shown to serve as tumor suppressor in that loss of RhoA activity promotes skin tumor formation." (PMID 33158289, 2020). "Together, our findings highlight the importance of targeting cancer cells and macrophages for skin cancer therapy, emerge a reverse link between ATX and RhoA and illustrate the benefit of p110δ PI3K inhibition as a combinatorial regimen for the treatment of skin cancers." (PMID 38182748, 2024).
Anxiety (5 papers, 2020 to 2025). Intense feelings of nervousness, tension, or panic often arise in response to interpersonal stresses. "A previously study indicated that increased RhoA expression was associated with decreased exploratory behavior, increased anxiety-like behavior, and decreased dendritic complexity of hippocampal neurons in CUMS-subjected rats." (PMID 40969943, 2025). "This disruption was mediated through the upregulated activity of downstream molecule‐RhoA‐GTPases, culminating in anxiety‐like behavior and impaired hippocampus‐dependent contextual fear memory." (PMID 39412367, 2025). "RhoA inhibitors not only increase myelination in injury models but also restore synaptic plasticity in an anxiety mouse model." (PMID 33115519, 2020).
autoimmune disease (5 papers, 2019 to 2023). A disorder resulting from loss of function or tissue destruction of an organ or multiple organs, arising from humoral or cellular immune responses of the individual to their own tissue constituents. "In line with this, T cell-specific RhoA deficient mice show reduced disease severity in autoimmune disorders such as EAE37." (PMID 34815397, 2021). "In recent years the importance of RhoA signaling in autoreactive immune cells for the onset and progression of autoimmune diseases has come into the focus of research." (PMID 31319592, 2019). "The RhoA/ROCK (Rho kinase) signaling pathway has been shown to be related to the pathogenesis of several autoimmune diseases; however, the specific mechanisms of RhoA/ROCK signaling in inflammatory bowel disease (IBD) remain elusive." (PMID 31262973, 2019). "Within the last years an increasing number of studies reported that RhoA and its downstream effector molecules have an essential function during infection processes and in the onset and progression of various autoimmune diseases, such as multiple sclerosis." (PMID 31319592, 2019). "Hence the conclusion can be drawn, that RhoA/ROCK and the corresponding downstream effector molecules might be suitable targets to develop new therapeutic approaches for the treatment of autoimmune diseases, such as MS." (PMID 31319592, 2019).
cardiomyopathy (5 papers, 2014 to 2023). A disease of the heart muscle or myocardium proper. "RhoA has been shown to play an important role in cardiac remodeling and cardiomyopathies; underlying mechanisms are however still poorly understood since the results derived from in vitro and in vivo experiments are still inconclusive." (PMID 33906663, 2021). "Of those enriched, a previous study has linked inhibition of RhoA signaling to adriamycin-induced cardiomyopathy." (PMID 25221565, 2014). "By contrast, other pathways clearly showed opposite trends, such as oxidative phosphorylation, necroptosis signaling, GP6 signaling in SDM, or fatty acid oxidation, ILK and RHOA signaling, and cardiomyopathy signaling pathway in LDM." (PMID 36835504, 2023). "The little existing data on RhoA function in the development and progression of cardiomyopathies show cardioprotective as well as deleterious effects of RhoA." (PMID 33906663, 2021). "In addition, in the heart, RhoA has been shown to play an important role in cardiac remodeling and cardiomyopathies." (PMID 33906663, 2021).
chronic heart failure (5 papers, 2018 to 2024). "On the one hand, tanshinone IIA regulates the expression of Caspase-9, CTGF, and RhoA protein levels by upregulating the level of miR-133 and exerting antimyocardial weight on chronic heart failure rats." (PMID 33763149, 2021).
chronic kidney disease (5 papers, 2013 to 2024). Impairment of the renal function secondary to chronic kidney damage persisting for three or more months. "In chronic kidney disease (CKD) and dialysis patients, increased oxidative stress is caused by the activation of NADPH oxidase and the activation of the RhoA/Rho kinase (ROCK) pathway." (PMID 39337956, 2024). "Based on some reports, Rac-1 and RhoA, as two key members of Rho GTPases, are listed as two mediators of podocyte dysfunction and therefore, their inhibition might be beneficial for handling chronic kidney diseases (CKDs)." (PMID 34861820, 2021). "In chronic kidney disease (CKD), RhoA deregulation is likely to be related to podocyte dysfunction." (PMID 24839453, 2014).
chronic myeloid leukemia (5 papers, 2012 to 2022). "This activity of Bcr has mostly been described in the context of the p210bcr-abl fusion from the Philadelphia chromosome that is associated with virtually all cases of chronic myeloid leukemia, and activates RhoA and various downstream targets thereof." (PMID 31461398, 2019). "In chronic myelogenous leukaemia (CML), p210bcr/abl1 activates RhoA leading to amoeboid migration, where inactivation of RhoA is able to reverse this process." (PMID 36699013, 2022).
chronic obstructive pulmonary disease (5 papers, 2013 to 2022). A chronic and progressive lung disorder characterized by the loss of elasticity of the bronchial tree and the air sacs, destruction of the air sacs wall, thickening of the bronchial wall, and mucous accumulation in the bronchial tree. "In case of chronic obstructive pulmonary disease (COPD), pulmonary endothelial dysfunction is tightly linked to RhoA deregulation." (PMID 24839453, 2014). "Recently, we observed that hyperactivation of RhoA conditions cardiomyocytes for the cardiac arrhythmia atrial fibrillation." (PMID 26193369, 2015).
colorectal tumor (5 papers, 2009 to 2022). "Recombinant adenovirus mediated RhoA and RhoC shRNA in tandem linked expression may inhibit the growth of human colorectal tumor xenografts in vivo." (PMID 20828398, 2010). "Similar to eIF3a, RhoA and Cdc42 represent higher expression in colorectal tumor tissues compared to adjacent normal tissues." (PMID 35300416, 2022). "Analyzing the gene profiles of 137 colorectal tumor samples in humans, it was indicated that RHOA is one of the most altered gene among RAS homologues, and RHOA expression shows a positive correlation with survival time." (PMID 33406731, 2021).
coronary artery diseases (5 papers, 2012 to 2023). "Recent studies have indicated that serum Neu5Ac plays a key role in severe coronary artery diseases, involving RhoA signaling pathway activation through a molecular docking test." (PMID 32351730, 2020). "Recent studies have indicated that N-acetylneuraminic acid (Neu5Ac) plays a key role in severe coronary artery diseases, involving RhoA signaling pathway activation, which is critically involved in cardiac fibrosis." (PMID 32351730, 2020). "Furthermore, recent studies have indicated that Neu5Ac plays a key role in severe coronary artery diseases, involving the activation of the RhoA signaling pathway, which is important for cardiac fibrosis." (PMID 32351730, 2020).
Crohn disease (5 papers, 2021 to 2024). A gastrointestinal disorder characterized by chronic inflammation involving all layers of the intestinal wall, noncaseating granulomas affecting the intestinal wall and regional lymph nodes, and transmural fibrosis. "Both RHOA-mutated SB-PCC cases arose in relatively young patients with Crohn disease." (PMID 36812376, 2023). "Given the high frequency of Crohn disease–associated cases in our cohort, it remains to be further investigated whether a few molecular findings, such as RHOA mutations, are specifically related to PCC histology or whether they are secondary to the molecular pathogenesis of Crohn-related SBAs." (PMID 36812376, 2023). "For example, there is a positive correlation between RhoA and TNF-α in the intestinal inflammatory tissues of Crohn’s disease patients, and RhoA/ROCK pathway activation stimulates the production of TNF-α and IL-1β." (PMID 38355537, 2024). "Most SB-PCCs (80%) were associated with Crohn disease, including both RHOA-mutated SB-PCCs, which featured a non-SRC-type histology, and showed a peculiar appendiceal-type, low-grade goblet cell adenocarcinoma (GCA)–like component." (PMID 36812376, 2023). "Our results indicate that the ATG16L1 T300A Crohn's disease-associated SNP causes a decrease in migration capacity in epithelial cells, mediated by an increase in SQSTM1 and ARHGAP18 protein and subsequent reduced RhoA activation." (PMID 33973626, 2021). "Activation of the RhoA/ROCK pathway stimulates TNF-α and IL-1β production, with a positive correlation observed between RhoA and TNF-α in the inflammatory tissues of Crohn's disease patients." (PMID 38491049, 2024).
Ewing sarcoma (5 papers, 2014 to 2025). A small round cell tumor that lacks morphologic, immunohistochemical, and electron microscopic evidence of neuroectodermal differentiation. "Tumor hypoxia exacerbates bone metastasis in Ewing sarcoma; this process is mediated by the hypoxia-induced activation of the NPY/Y5R system, leading to RhoA overstimulation, cytokinesis failure and the formation of polyploid Ewing sarcoma cells." (PMID 37373115, 2023). "In this regard, it has been shown that RHOA is the direct geranylgeranylated effector signaling to the YAP/TAZ pathway, which plays important roles in the tumorigenesis of Ewing sarcoma." (PMID 35565457, 2022).
gastric tumor (5 papers, 2008 to 2022). "In particular, a high percentage of mutations in RhoA, which due to their location are believed to increase activity, were found in genetically stable gastric tumors." (PMID 36313672, 2022). "We have shown that NET1 is a key player in LPA-induced activation of RhoA and the subsequent migration and invasion of gastric tumour cells." (PMID 18827818, 2008). "Since the RHOA mutation can lead to the fatty acids production in TME by gastric tumor cells, we speculate that in the TME of LIHC, maybethe upregulated PRC1 recruits Tregs by regulating RHOA and its RHO family." (PMID 35983074, 2022).